IL7R (interleukin 7 receptor)
Diseases named in the same sentence as IL7R in open-access papers (continued):
Sharing a sentence is not in itself a finding about the gene and the disease.
lymphopenia (38 papers, 2009 to 2025). Reduction in the number of lymphocytes. "STING GOF T cells display signs of TCR and IL-7R engagement since the naive T cell stage, consistent with lymphopenia-associated signals provided by (auto)antigen and IL-7-mediated stimulation, respectively." (PMID 40804163, 2025). "Indeed, defective signaling in IL-7−/− or IL-7R−/− knock out mice results in early thymic development arrest and lymphopenia, while in humans inactivating mutations in the IL-7Rα or γc cause severe combined immunodeficiency." (PMID 28872614, 2017). "This shows that lymphopenia-associated IEC hyperplasia can occur independently of BM-derived IL-7R+ ILC and might result form IL-7R signaling in IEC." (PMID 22384106, 2012). "Taken together, our results suggest that the lymphopenic environment impacts T cells in STING GOF mice through TCR and IL-7R engagement since the naive T cell stage, pathways which are known to govern lymphopenia-induced homeostatic proliferation." (PMID 40804163, 2025). "We searched PubMed, Embase, and Web of Science from inception to April 24, 2025, using terms such as Interleukin-7, CD127, CYT107, interleukin-7 receptor, sepsis, septic shock, and lymphopenia." (PMID 41158471, 2025). "Autosomal recessive mutations that disrupt IL-7Rα chain expression give rise to a severe combined immunodeficiency (SCID), which is characterized by lymphopenia and a T−B+NK+ phenotype." (PMID 38587703, 2024). "This is due to internalization of IL7R during episodes of severe lymphopenia and also due to the fact that if T cells are decreased, gating lymphocytes for IL7R expression is not an appropriate strategy." (PMID 31572360, 2019). "Our experiments revealed that IL-15Rβ and IL-7Rα expression was up- and down-regulated, respectively, on transferred Te cells in an early phase post T-cell transfer in lymphopenia." (PMID 27158441, 2016). "We next extended these in vitro analyses, and reveal, for the first time, a distinct in vivo modulation of IL-7Rα and IL-15Rβ expression on transferred Te cells in lymphopenia." (PMID 27158441, 2016). "IL7R signaling promotes T-cell homeostatic proliferation during lymphopenia." (PMID 38956225, 2024). "In such a scenario the immunomodulatory activity of anti-IL-7Rα mAbs could be exploited while avoiding long-term side effects such as lymphopenia and immunodeficiency." (PMID 30908554, 2019). "In this study, we reported that a strict antagonist of IL-7Rα prevents on the long-term memory T cell mediated skin inflammation in primates, without induction of lymphopenia or polyclonal T cell functional or metabolic deficiencies." (PMID 31225460, 2018). "“Antagonist-only” antibodies against the IL-7R prevented long-term memory T-cell-mediated skin inflammation in primates, even after chronic antigen stimulation, without inducing lymphopenia or polyclonal T-cell functional or metabolic deficiencies." (PMID 30367166, 2018). "IL-7 is known to drive the homeostatic expansion of human naive CD4+ T cells during early life lymphopenia, which led us to examine whether differences in IL-7 receptor (IL-7R) signaling might contribute to the preferential expansion of prenatal naive PLZF+CD4+ T cells." (PMID 37856221, 2023). "Collectively, these data suggest a mechanism of prolonged, lymphopenia-driven increase of systemic IL-7 and IL-15 concentrations after acute SARS-CoV-2 infection, which sustains increased IL-2R and decreased IL-7R expression." (PMID 41310351, 2025). "IL-7Rα expression was significantly downregulated in CD4+ and CD8+ naive and memory T cells from STING GOF mice (Fig. EV5A,C), indicating that T cell lymphopenia impacts T cell fate at early stage in the periphery of STING GOF mice." (PMID 40804163, 2025). "For examples, monocyte alterations (CD74, CIITA mRNA), lymphopenia (CD3, IL7R mRNA), increased anti-inflammatory response (IL10, IL1RN mRNA), altered IFN response (OAS2, IFNG mRNA) were observed." (PMID 36389738, 2022).
lymphopenia (continued). "Both patients showed a combined immunodeficiency as proven by a profound lymphopenia, a lack of thymic output, and defective IL7Rα expression on lymphocytes." (PMID 33203071, 2020). "Our results indicate that a relatively low dose of anti-IL-7Rα M595 can protect mice from Hb-induced colitis without inducing lymphopenia to the extent seen with the high dose of anti-IL-7Rα M595." (PMID 23057802, 2012). "Similarly, lymphopenia has not been reported in recent phase I clinical trials with two different site-1 anti-IL-7Rα in healthy volunteers or in type 1 diabetic adult patients." (PMID 31225460, 2018). "Further dose–response studies would be needed, but these results suggest there may be a therapeutic window for anti-IL-7Rα in inflammatory disease settings whereby T-cell function would be controlled without significant lymphopenia." (PMID 23057802, 2012). "Therefore, the results are in favor of an increased IL-7R engagement, and we can suggest that STING GOF T cells are more activated by IL-7 because they will encounter an abnormal amount of IL-7 per T cell, compared to a physiological situation, as described in lymphopenia-induced proliferation." (PMID 40804163, 2025).
Immunodeficiency (37 papers, 2011 to 2026). Failure of the immune system to protect the body adequately from infection, due to the absence or insufficiency of some component process or substance. "According to previous studies, the loss of IL-7 and IL-7R can lead to severe immune deficiency, and IL-7R acts a vital role in the generation and long-term maintenance of memory CD8+ T cells." (PMID 38748299, 2024). "Previous reports have shown that IL7R blocks the development of T cells, and patients with IL7R-inactivating mutations present with severe combined immunodeficiency." (PMID 37449207, 2023). "Bi-allelic mutations in the IL-7Rα chain abolish T cell development and function resulting in severe combined immunodeficiency disease." (PMID 35418989, 2022). "The IL-7/IL-7R pathway is essential for lymphocyte development and disturbances in the pathway can lead to immune deficiency or T cell mediated destruction." (PMID 31024566, 2019). "Loss-of-function mutations and some polymorphisms of the IL7Rα were associated to immunodeficiency and inflammatory diseases, respectively." (PMID 31817502, 2019). "While mutations in IL7Rα cause a T(−), B(+), and NK(+) immunodeficiency, the latter two mutations result in a T(−), B(+), and NK(−)." (PMID 28450869, 2017). "For example, mutations in IL2RA and IL7R cause immunodeficiency and mutation in TYK2 and STAT3 have been reported to cause hyper-IgE syndrome." (PMID 21552549, 2011). "IL7R inactivation causes severe combined immunodeficiency in humans." (PMID 35898935, 2022). "Previous studies have shown that signaling through IL-7R is essential in the developmental process and regulation of lymphoid cells, and disruption of the IL-7R signaling pathway may lead to skewed T cell distribution and cause immunodeficiency." (PMID 34905486, 2021). "Downregulated genes in CD69+ CD4+ T cells were involved in cell adhesion (PTPRC; -0.38log2FC), differentiation (CD44; -0.38log2FC), and immunodeficiency (IL7R; -0.42log2FC) pathways." (PMID 41208955, 2025). "Individuals with mutations of IL-7Rα, IL-2R common γ chain (IL2Rγ), and JAK3 develop severe combined immunodeficiency." (PMID 28450869, 2017). "Infants with biallelic IL7R loss-of-function variants have severe combined immune deficiency (SCID) characterized by the absence of autologous T lymphocytes, but normal counts of circulating B and NK cells (T–B+NK+ SCID)." (PMID 39352394, 2024). "Accordingly, targeting IL-7Rα using specific antibodies may also affect B cells and result in immunodeficiency in obese patients." (PMID 37266430, 2023). "Therefore, modulation of IL-2/IL-2R and IL-7/IL-7R signaling with biological therapies has great potential as countermeasures to restore immune dysfunction of crew members." (PMID 37624890, 2023). "This statement suggests that the activation of receptor complex {IL7R, IL2RG} may activate {JAK1, JAK3} to cause immunodeficiency disease." (PMID 27819359, 2016). "To prove that antagonist anti-IL-7Rα mAbs induced antigen-specific hyporesponsiveness and not broader immunodeficiency, we first assessed ex vivo polyclonal activation of baboon PBMCs before and during treatment." (PMID 30367166, 2018).
rheumatoid arthritis (34 papers, 2009 to 2025). A chronic, systemic autoimmune disorder characterized by inflammation in the synovial membranes and articular surfaces. "Systemic anti-IL7R Ab treatment significantly suppressed the induction and progression of collagen-induced arthritis, a mouse model of human rheumatoid arthritis." (PMID 40323267, 2025). "IL-7 and IL-7R signalling pathways are important for T cell population maintenance and are involved in many inflammatory conditions, such as diabetes and rheumatoid arthritis." (PMID 34371826, 2021). "Interleukin-7 receptor alpha (IL-7Rα) represents a biomarker with potential applications in rheumatoid arthritis (RA) diagnosis and therapy." (PMID 27729062, 2016). "The cytokines interleukin (IL)-7 and thymic stromal lymphopoietin (TSLP) signal through the IL-7R subunit and play proinflammatory roles in experimental arthritis and rheumatoid arthritis (RA)." (PMID 26110994, 2015). "In case of rheumatoid arthritis both, membrane and soluble IL7R, are induced by pro-inflammatory cytokine, especially TNFα." (PMID 25302706, 2014). "These include PTPN22, associated with systemic lupus erythematosus (SLE), rheumatoid arthritis (RA), T1D, and Graves' Disease (GD), STAT4, associated with SLE and RA, and the IL7R and KIAA0350 gene regions, which are shared between T1D and MS." (PMID 19119414, 2009). "Accordingly, the effect of IL-7 and IL-7R in rheumatoid arthritis is worth exploring." (PMID 37217704, 2023). "However, IL-7R mediates inflammatory diseases, including ulcerative colitis, rheumatoid arthritis, and autoimmune diabetes." (PMID 35159120, 2022). "We investigated expression levels of IL7R relative to disease status for type 2 diabetes (T2D), chronic obstructive pulmonary disease (COPD) and rheumatoid arthritis (RA) in the offspring of long-lived individuals and controls." (PMID 26566388, 2015). "Coincidently, a recent study of rheumatoid arthritis (RA) showed that the high responsiveness to IL-7 stimulation together with the synergy of IL-7 and M1-promoting factors (e.g., MIP-1b, TNF-a) can enhance the expression of joint myeloid IL-7R and further exacerbate arthritis." (PMID 32117217, 2020).
Autoimmunity (33 papers, 2011 to 2025). The occurrence of an immune reaction against the organism's own cells or tissues. "Here the authors show that allelic variation at rs6897932, an autoimmune GWAS risk allele at IL7R, regulates surface and soluble IL-7R in stimulated monocytes, indicating a function of monocytes in IL-7-related autoimmunity." (PMID 31594933, 2019). "Aberrant expression of soluble (s) and membrane-associated (m) IL-7R molecules is associated with development of autoimmunity and immune failure in acquired immune deficiency syndrome (AIDS) patients." (PMID 28582466, 2017). "Given that an increased proportion of IL-7R-positive cells is a common mechanism underlying the pathogenesis of autoimmunity, we found that specific depletion of this cell population abrogated the progression of disease." (PMID 28878234, 2017). "This single nucleotide polymorphism causes alternative splicing in exon 6 of the IL7R gene with possible influence of the autoimmunity." (PMID 25422737, 2014). "Three independent studies showed that elevated sIL-7R is associated with an increased risk of to develop autoimmunity, a situation which maybe at first glance counter-intuitive: since soluble IL-7R may bind free IL-7 and neutralizes its effects." (PMID 24946690, 2014). "Membrane-bound IL-7R mediates IL-7 signalling, while soluble IL-7R provides regulatory control, amplifying IL-7 signalling and enhancing autoimmunity." (PMID 38675377, 2024). "Together, our data suggest that anti-IL-7Rα antibodies promote two key mechanisms of protection against autoimmunity: increased expression of co-inhibitory receptors and increased Treg activity." (PMID 28356069, 2017). "Meanwhile, in the context of autoimmunity, recent studies have identified the antagonistic effects of IL-7Rα and the inhibitory receptor PD-1 on effector T cells as essential parts of the cell-intrinsic immunoregulatory program of T cell effector function." (PMID 27912762, 2016). "In summary, our results provide new insights into the regulation of intestinal homeostasis and have important implications for the design of clinical protocols targeting the IL-7/IL-7R signaling pathway to treat T cell-mediated autoimmunity and cancer." (PMID 22384106, 2012). "The DR relationship characterizing the effects of PF-06342674 on the Treg:TEM T cell ratio provides evidence that IL-7Rα blockade may shift the balance from autoimmunity towards immune tolerance." (PMID 31900603, 2020). "Overall, the observed increase in the Treg:TEM ratio provides evidence that IL-7Rα blockade may shift the balance from autoimmunity towards immune tolerance." (PMID 31900603, 2020). "In the context of autoimmunity, our data demonstrate that several major determinants of T cell encephalitogenicity, including T-bet, IL-12, and IL-6, skew IL-7Rα/PD-1 balance towards IL-7Rα, favoring an encephalitogenic phenotype of myelin-specific CD4 T cells with enhanced effector function." (PMID 27912762, 2016). "The suppression of IL-7Rα expression and the upregulation of inhibitory receptors (PD-1, etc.)are essential parts of the cell-intrinsic immunosuppressive program regulating T effector functions to prevent autoimmunity." (PMID 27912762, 2016). "Skewing of the T helper balance to Th2/Treg recruited at sites of inflammation is one potential mechanism by which higher IL7Rα signaling might protect against autoimmunity." (PMID 24147013, 2013). "CD8+CD122+ T cells contain an abundant subset of PD-1+ cells that are CD8+ Treg cells; these Treg cells (CD8+CD122+PD-1+) are capable of suppressing autoimmunity and alloimmunity mainly through their secretion of IL-10, and are largely CD127 (encoded by IL-7Rα) negative." (PMID 29780389, 2018). "It is tempting to speculate that, in concert with increased IL7R expression in patients with high cortisol and mild MS, this may indicate the presence of mechanism that serves to maintain a population of T cells with a regulatory phenotype to limit autoimmunity." (PMID 31023360, 2019).
Autoimmunity (continued). "Due to the multiple immunoregulatory pathways induced in anti-IL-7Rα-treated NOD mice, it will be a challenging endeavor to unequivocally demonstrate the contribution of each to controlling autoimmunity." (PMID 28356069, 2017). "The excess IL-7 is not, however, consumed by CD4–CD8– T cells due to permanent down-regulation of IL-7Rα (CD127), but instead supports proliferation of autoreactive T cells and progression of autoimmunity." (PMID 22102903, 2011). "Given the key role for anti-TNF therapies in the treatment of many autoimmune conditions, we tested whether released TNF may drive monocyte IL7R induction in an autocrine manner by incorporating the anti-TNF monoclonal antibody Infliximab in the media with LPS." (PMID 31594933, 2019).
Sepsis (31 papers, 2011 to 2025). Sepsis is defined as life-threatening organ dysfunction caused by a dysregulated host response to infection. "Some clinical studies have also suggested that the IL-7/IL-7R signaling pathway is associated with improved lymphocyte function in sepsis patients." (PMID 39654893, 2024). "Sepsis patients exhibit substantial alterations in IL-7, IL-7R, and associated factors." (PMID 41158471, 2025). "Moreover, IL-7R appears to be associated with sepsis mortality." (PMID 41158471, 2025). "Bioinformatics analysis suggests that IL-7R may also serve as an underlying marker for sepsis." (PMID 41158471, 2025). "Soluble IL-7R (sIL-7R) levels differ between sepsis survivors and sepsis deaths in plasma, with higher sIL-7R associated with higher mortality." (PMID 41158471, 2025). "During sepsis, IL-7R levels increase, particularly on CD4+ and CD8+ T cells, and remain elevated for 1–4 days." (PMID 41158471, 2025). "Employing endogenous IL-7 and IL-7R as prognostic markers in sepsis currently lacks a well-defined standard." (PMID 41158471, 2025). "Some studies had shown that the level of IL7R in sepsis was low expressed, which was consistent with our findings." (PMID 39654893, 2024). "Studies had shown that the level of IL7R in sepsis was significantly reduced, which was consistent with our results." (PMID 36199375, 2022). "We analyzed the immune targets of immune-related drugs to predict their potential use in sepsis and showed that nine target loci (CSF2RA/B, CSF3R, IFNGR1/2, IL7R, PDL1, CTLA4, and LAG3) differed in the high-/low-risk block." (PMID 36389695, 2022). "It showed association with CD2, IL2RB, and IL7R in adult SIRS and KLRG1 and TGFBR3 in adult sepsis, among others." (PMID 32318053, 2020). "Additionally, plasma IL-7R concentrations are higher in sepsis survivors than in those who succumb to the condition, at least 2 days after onset." (PMID 41158471, 2025). "In clinical settings, endogenous IL-7 and IL-7R have shown promise as prognostic markers in sepsis." (PMID 41158471, 2025). "In patients with sepsis, IL-7R mRNA levels are higher than in healthy individuals." (PMID 41158471, 2025). "The concentration of IL-7R in peripheral blood were highest in sepsis group and IL-7 antibody treatment could decrease the concentration of IL-7R." (PMID 37113759, 2023). "Our works strongly suggested that the deregulation of lncRNA LINC00861 correlated with IL7R might promote sepsis development through mediating functions of T cells." (PMID 34483898, 2021). "Artificial intelligence-driven multi-omics methods, including genomics, microbiome profiling, and radiomics, could facilitate the stratification of patients with sepsis according to IL-7/IL-7R mRNA variability, microbial ecology, or metabolic–epigenetic states." (PMID 41158471, 2025). "With the presented results in this study, demonstrating that LPS-activated tolerant CD14+ monocytes upregulate IL7R on the cell surface, it can be speculated that IL-7 administration during sepsis will also affect the IL7R-positive tolerant monocyte population." (PMID 28404994, 2017). "Based on the discussion and analysis, it is reasonable to assume that IL7R, GZMA and CD8A possess significant potential value in the diagnosis and prediction of sepsis." (PMID 39654893, 2024). "Our findings revealed significant decreases in CD4, CD3e, IL-7R, CD5, CD247, CD2, CD40LG, ITK, and KLRB1, and significant elevations in MMP9, LCN2, and RETN in sepsis-induced ARDS compared to controls." (PMID 37822934, 2023). "We also found that the expression level of CD3D, CD3E, CD4, CD28, IL7R, and LCK was statistically different between sepsis and normal groups, indicating their potential role in the development of sepsis." (PMID 37113759, 2023). "The lower expression of the hub genes (CD3D, CD3E, CD4, CD28, IL7R and LCK) was observed in sepsis samples, which was consistent in all the six hub genes." (PMID 37113759, 2023).